EGFL7 (EGF like domain multiple 7)
Diseases named in the same sentence as EGFL7 in open-access papers (continued):
Sharing a sentence is not in itself a finding about the gene and the disease.
cognitive decline (2 papers, 2017 to 2023). "Future work will reveal whether the downregulation of EGFL7 and similar factors may be applied to reconstitute or at least increase the aNSC pool in aged animals to delay the cognitive decline happening during aging." (PMID 28656980, 2017).
esophageal squamous cell carcinoma (2 papers, 2019). Esophageal squamous cell carcinoma (ESCC) is a type of esophageal carcinoma (EC) that can affect any part of the esophagus, but is usually located in the upper or middle third. "Aberrantly upregulated DNMT1 and the downregulation of miR-126 associated with promoter hypermethylation of its host gene EGFL7 were observed in esophageal squamous cell carcinoma (ESCC)." (PMID 31850200, 2019).
experimental autoimmune encephalomyelitis (2 papers, 2018 to 2024). An autoimmune demyelinating disease of the central nervous system that is produced experimentally in animals by the injection of homogenized brain or spinal cord in Freund's adjuvant. "And Egfl7 was increased in CNS vasculature of mice with experimental autoimmune encephalomyelitis (EAE)." (PMID 39013903, 2024). "We discovered that the expression of ECM epidermal growth factor-like protein 7 (EGFL7) is increased in the CNS vasculature of patients with multiple sclerosis (MS), and in mice with experimental autoimmune encephalomyelitis (EAE)." (PMID 29483510, 2018). "The role of EGFL7 in neuroinflammation has not been studied, but as EGFL7 can influence EC survival and activation, we hypothesized that it could play a significant role in the animal model of MS, namely experimental autoimmune encephalomyelitis (EAE)." (PMID 29483510, 2018).
melanoma (2 papers, 2021 to 2024). A malignant, usually aggressive tumor composed of atypical, neoplastic melanocytes. "HB-EGF inversely correlates with Egfl7, the host gene of miR-126 expression in melanoma." (PMID 39419989, 2024). "Like in melanoma, we found an inverse correlation between the expression of HB-EGF and Egfl7 in tumor tissue of COAD patients (Spearman’s rho value −0.0473445, p = 0.3118836; n = 457; data analysis using Timer)." (PMID 39419989, 2024). "A recent study demonstrated that treatment of ECs with melanoma cell-derived exosome enhanced VE-Cadherin, uPAR, and EGFR upregulation in ECs, resulting in a tumor EC phenotype, and through EGFR gave EGFL7 a chance to promote neoangiogenesis." (PMID 33804387, 2021).
pleural mesothelioma (2 papers, 2019 to 2021). A neoplasm that arises from the mesothelial cells of the pleura. "Methylation-associated silencing of miR-126 and its host gene EGFL7 has been demonstrated in pleural mesothelioma, suggesting an association between EGFL7 and miR-126." (PMID 33917022, 2021). "A study reports methylation-associated silencing of miR-126 and its host gene EGFL7 in pleural mesothelioma, suggesting an association between EGFL7 and miR-126 in cancer." (PMID 31245291, 2019). "A previous study has reported methylation-associated silencing of miR-126 and its target gene EGFL7 in pleural mesothelioma suggesting a close association between EGFL7 and miR-126 in cancers." (PMID 31245291, 2019).
preeclampsia (2 papers, 2022 to 2025). Preeclampsia is a hypertensive disorder of pregnancy that is characterized by new-onset hypertension with proteinuria presenting after 20 weeks of gestation, and depending on mild or severe forms may initially present with severe headache, visual disturbances, and hyperreflexia. "Finally, circulating EGF Like Domain Multiple 7 (EGFL7) has been used to classify isolated FGR and preeclampsia at different gestational stages." (PMID 36478738, 2022).
systemic sclerosis (2 papers, 2013 to 2022). A chronic disorder, possibly autoimmune, marked by excessive production of collagen which results in hardening and thickening of body tissues. "Moreover, in systemic sclerosis, miR126 has been demonstrated to contribute to the downregulation of the angiogenic factor EGFL7 and may influence fibrosis via collagen modulation." (PMID 36292960, 2022).
adenoma (1 paper, 2023). A neoplasm arising from the epithelium. "In research on pituitary samples obtained from patients with growth hormone-producing adenomas, the overexpression of EGFL7 positively correlated with the activation of EGFR (p-EGFR)." (PMID 37446128, 2023).
allergic asthma (1 paper, 2024). A asthma with a basis in a pathological type I hypersensitivity reaction. "The genes associated with mucin production (GAL3ST2), leukotriene synthesis (GPX4), Th2-mediated allergic asthma (PTBP1, ZFPM1, SBNO2, and EGFL7), and IgE mediated allergy (PAK2) were also represented in our polygenic prediction models of ICS response." (PMID 38540988, 2024).
atherosclerosis (1 paper, 2023). A disease characterized by the build-up of fatty material and calcium deposition in the arterial wall resulting in partial or complete occlusion of the arterial lumen. "One study discovered that increasing EGFL7 expression enhances neoangiogenesis within plaques and promotes the development of atherosclerosis." (PMID 37109540, 2023).
B-cell acute lymphoblastic leukemia (1 paper, 2022). A neoplasm of lymphoblasts committed to the B-cell lineage, typically composed of small to medium-sized blast cells. "Clinically, a previous study reveals that EGFL7 serves as a potential diagnostic marker in B-cell acute lymphoblastic leukemia (B-ALL) patients." (PMID 34635968, 2022).
bladder cancer (1 paper, 2024). "The receptor tyrosine kinase ERBB2 was primarily amplified in bladder cancer, while FGFR4 and EGFL7 alterations were mainly seen among RCC cases." (PMID 38398121, 2024).
brain tumor (1 paper, 2018). "Inhibition of EGFL7 using specific antibodies reduced the vascularization of experimental brain tumors and increased survival." (PMID 30065025, 2018). "Interestingly, increased activation of Cdc42, as induced by EGFL7, has been reported to reduce the survival of brain tumor‐bearing mice." (PMID 30065025, 2018). "Elevated expression of EGFL7 may still be detected in angiogenic vessels during tissue repair or regeneration as well as in several tumor types, including colon, gastric, breast, kidney, liver, and brain tumors." (PMID 30065025, 2018). "Data supported the fact that EGFL7 was indeed expressed in stromal cells but was absent from brain tumor cells." (PMID 30065025, 2018).
Breast Invasive Carcinoma (1 paper, 2025). "We first assessed expression levels of miR-126 and its host gene EGFL7, in human BC tissues using data from The Cancer Genome Atlas: Breast Invasive Carcinoma (TCGA-BRCA) database." (PMID 39796183, 2025).
chondrosarcoma (1 paper, 2020). A malignant cartilaginous matrix-producing mesenchymal neoplasm arising from the bone and soft tissue. "We observed increased varying secretion of EGFL7 in OS tissues compared with chondrosarcoma (CS) tissues." (PMID 32117731, 2020).
gastric tumors (1 paper, 2014). "In excised human gastric tumors, expression of EGFL7 was positively correlated with expression levels of the mesenchymal marker vimentin and the EMT-associated transcription repressor Snail, and negatively correlated with expression of the epithelial cell marker E-cadherin." (PMID 24945379, 2014).
Hypertension (1 paper, 2018). The presence of chronic increased pressure in the systemic arterial system. "However, beyond increasing the efficacy of bevacizumab, anti‐EGFL7 treatment might serve to reduce bevacizumab‐specific toxic side effects such as hypertension or proteinuria." (PMID 30065025, 2018).
ischemic stroke (1 paper, 2024). A stroke disorder caused by obstruction of blood flow to the brain, due to thrombotic (local blood clot formation) or embolic (due to a blood clot or other material traveling from another site) event. "We investigated its relevance in ischemic stroke by examining the expression of Egfl7 during brain vascular injury." (PMID 39013903, 2024).
laryngeal carcinoma (1 paper, 2015). Carcinoma that arises from the laryngeal epithelium. "A similar relationship has been demonstrated by analysing EGFL7, using IHC in samples from patients with laryngeal carcinomas." (PMID 25592646, 2015).
lung tumors (1 paper, 2018). "Levels of markers regulated by histone acetylation such as PTEN, MARCKs, EGFL-7 (almost significant decrease), FGFRL-1, SNAIL-1, P63, and k-RAS were significantly reduced in the lung tumors compared to non-tumors only in patients with LC-COPD." (PMID 29371906, 2018).
lymph node metastases (1 paper, 2015). "The correlation between VA estimates of EGFL7 and miRNA-126 in the lymph node metastases only reached borderline significance, tentatively supporting a positive correlation between the estimates." (PMID 25592646, 2015).
malignant brain tumors (1 paper, 2018). "In order to overcome this shortcoming, we explored the role of a novel proangiogenic factor termed EGFL7 in malignant brain tumors." (PMID 30065025, 2018).
metastatic disease (1 paper, 2015). "The results may suggest a possible clinical importance of EGFL7 at early disease stages and a coordinated regulation of this angiogenic couple in localised as well as metastatic disease." (PMID 25592646, 2015).
multiple myeloma (1 paper, 2022). "We aimed to investigate the relationship among epidermal growth factor–like protein-7 (EGFL7), integrin subunit beta 3 (ITGB3), and Kruppel-like factor 2 (KLF2) expressions and their clinical implication in multiple myeloma (MM)." (PMID 34635968, 2022).
neuroblastoma (1 paper, 2024). Neuroblastoma (NB) is the most common solid, extracranial childhood tumor. "We analyzed the expression of endothelial markers (EGFL7, FLT1, PTPRB33), mesenchymal cells (COL1A2, COL1A1, PDGFRB34,35) and immune markers (ITGAM, CD247, PTPRC36–38) in MYCN-amplified neuroblastoma patient samples (with at least 90% tumor purity) and tumors from Protocol #4." (PMID 39367051, 2024).
neurofibroma (1 paper, 2021). An intraneural or extraneural neoplasm arising from nerve tissues and neural sheaths. "We have identified potential endothelial cells markers (e.g. SERPINE1, EGFL7, CSF3) based on their low expression in other non-endothelial neurofibroma cells." (PMID 33413690, 2021).
Ovarian cyst (1 paper, 2019). The presence of one or more cysts of the ovary. "Compared to ovarian cyst and benign GCT tissues, EGFL7 was highly expressed in malignant GCT tissues, which is diametrically opposed to the expression of miR-126 in GCT tissues." (PMID 31245291, 2019).
ovarian serous carcinoma (1 paper, 2022). "Aim: to analyze mRNA expression of EGFL7 within the tumor microenvironment of high-grade ovarian serous carcinoma and its association with a number of intraepithelial CD4+/CD8+ lymphocytes and ICAM-1 expression." (PMID 35630004, 2022). "Methods: qPCR analysis of EGFL7 mRNA in cancer cells and adjacent stromal endothelium microdissected from formalin-fixed paraffin-embedded tumors of 59 high-grade ovarian serous carcinoma patients, was performed." (PMID 35630004, 2022).
primary effusion lymphoma (1 paper, 2018). A large B-cell lymphoma located in the body cavities, characterized by pleural, peritoneal, and pericardial fluid lymphomatous effusions and that is always associated with human herpes virus-8 (HHV-8). "Significant upregulation of EGFL7 in primary effusion lymphoma cell lines suggest that EGFL7 likely plays an important role in KSHV induced malignancies." (PMID 29416688, 2018). "Our data show that KS tumors as well as primary effusion lymphoma cells have increased levels of EGFL7 compared to the uninfected cells." (PMID 29416688, 2018). "Our results revealed that EGFL7 transcript and protein expression were significantly elevated in latently KSHV-infected primary effusion lymphoma cells, BC3 and BCBL1, compared to the KSHV-negative BJAB cells." (PMID 29416688, 2018). "To this end, we analyzed the EGFL7 mRNA levels in KSHV-infected primary effusion lymphoma cell lines, BCBL1 and BC3 and compared with a KSHV negative cells line, BJAB." (PMID 29416688, 2018).
vascular malformation (1 paper, 2023). A non-neoplastic disorder that is the result of defects of vascular morphogenesis. "Indeed, the treatment with SNC led to vascular malformation and EGFL7 levels being decreased." (PMID 37593220, 2023).
tumor (67 papers, 2010 to 2025). "Studies have shown that high EGFL7 expression is associated with poor prognosis in different tumor types, such as gastric cancer and CRC9,10." (PMID 37957249, 2023). "High EGFL7 levels are associated with higher tumor grade and poor prognosis as a potential cancer target." (PMID 36530974, 2022). "The presence of EGFL7 mRNA transcripts in the epithelium and/or endothelium of tumor microenvironment was associated with a lower influx of adaptive immune effectors (CD4+ and CD8+ lymphocytes) into cancer nests." (PMID 35630004, 2022). "Here we summarize recent studies on the role of the ECM-linked angiocrine factor EGFL7 in primary tumor growth, neoangiogenesis, tumor metastasis by enhancing epithelial-mesenchymal transition, alterations in ECM rigidity, and drug resistance." (PMID 33804387, 2021). "Our cell experiment also found that cisplatin can cause the down-regulation of EGFL7 expression in tumor cells, but tumor cells are easy to produce drug resistance." (PMID 32117731, 2020). "Our previous findings showed that there was a tumor grade-dependent up-regulation of EGFL7 in OS tumor tissues, where high EGFL7 expression levels were associated with a worse prognosis." (PMID 32117731, 2020). "In summary, our research reveals that URRCC functions as a tumor-inducer to control the ccRCC progression via modulating URRCC/EGFL7/P-AKT/FOXO3 positive feedback loop and cause cascading effects in ccRCC." (PMID 30953521, 2019). "The inhibition of EGFL7 expression can prevent lumen formation and induce the loss of function of blood vessels, thereby suppressing tumor growth and metastasis." (PMID 29363485, 2018). "Methylation-associated regulation of MiR-126 and its host gene EGFL7 has been described in other tumours." (PMID 30223817, 2018). "Using an in vitro co-culture system, this study aimed to simulate the interaction between tumor cells and endothelial cells in vivo and to investigate the effect and the underlying mechanisms of EGFL7 expression in both cell types." (PMID 29363485, 2018). "Expression of EGFL7 in tumor cells may be associated with important pathways that can alter functions related to tumor invasive processes, preventing recurrence and metastatic process." (PMID 37957249, 2023). "We conclude, therefore, that the low expression of EGFL7 in the tumor cells of patients diagnosed with CRC may be associated with high expression of VEGF2, thus leading to an increase in lymphatic invasion and greater lymphangiogenesis." (PMID 37957249, 2023). "Therefore, EGFL7 contributes to the hallmark excessively branched and disorganized architecture of tumor endothelium." (PMID 33804387, 2021). "EGFL7 is produced by cancer-associated ECs and certain tumor cell types." (PMID 33804387, 2021). "However, a general loss of EGFL7 significantly prolonged the median survival time of tumor‐bearing mice from 35.5 days in WT littermates to 44 days in EGFL7 KO animals." (PMID 30065025, 2018). "Recent studies have indicated that high tumor expression levels of EGFL7 may be associated with poor prognosis in several different malignancies." (PMID 28539619, 2017). "In the present descriptive study we describe the expression of EC-associated EGFL7 and miRNA-126 by estimating the vessel area fractions in primary tumours of different stages and in paired samples of primary tumours, regional lymph node metastases, and distant metastases from patients with CRC." (PMID 25592646, 2015). "In addition, the A allele of rs2297538 was significantly associated with a decreased NSCLC risk (OR = 0.68, 95% CI: 0.52~0.88), and the expression of EGFL7 and miR-126 was significantly lower in rs2297538 homozygous G/G tumor tissue than in A/G+A/A tumor tissue (P = 0.01 and P = 0.002)." (PMID 35494025, 2022). "EGFL7, which is associated with the ECM, is linked to primary tumor growth, angiogenesis, tumor metastasis, and drug resistance, highlighting the multifaceted role of angiocrine factors in cancer progression." (PMID 40521189, 2025).